PPARG (peroxisome proliferator activated receptor gamma)
Diseases named in the same sentence as PPARG in open-access papers (continued):
Sharing a sentence is not in itself a finding about the gene and the disease.
Right ventricular hypertrophy (4 papers, 2007 to 2024). In this case the right ventricle is more muscular than normal, causing a characteristic boot-shaped (coeur-en-sabot) appearance as seen on anterior- posterior chest x-rays. "Mice with targeted endothelial or smooth muscle cell deletion of Pparγ spontaneously developed PAH with increased right ventricular hypertrophy and muscularization of the distal pulmonary arteries, whereas restoration of PPARγ has been reported to reverse experimental PH." (PMID 38903104, 2024). "However, PPAR-mediated responses alone may not explain the observed effects, as treatment of hypoxia-exposed mice with the PPARγ agonist rosiglitazone attenuates rather than promotes the increase in pulmonary artery pressure and right ventricular hypertrophy." (PMID 34943801, 2021).
rosacea (4 papers, 2021 to 2025). A chronic erythematous skin disorder that affects the face. "Our evidence indicated that LNA hyperactivates PPARγ signaling in the epidermis, a phenomenon observed in both rosacea patients and mouse model." (PMID 40191007, 2025). "Based on the ol-DEGs, we revealed the TF regulatory network in AD/rosacea, indicating a central role of the 24 TFs in regulating the pathogenesis of AD and rosacea, including PPARG, STAT4, sox9, and RORA." (PMID 34899707, 2021). "In rosacea, proteomic and transcriptomic investigations have revealed enrichment of neurodegeneration-related proteins such as SNCA, GSK3B, and HSPA8, as well as regulatory hubs including PPARG, STAT4, and RORA, which converge on NF-κB, IL-17, and TNF signaling pathways." (PMID 41465136, 2025).
silicosis (4 papers, 2019 to 2025). Silicosis is a respiratory disease caused by breathing in (inhaling) silica dust. "First, foam cells represent only a small minority of the total cell population of lung macrophages in patients with early stage silicosis, making their overall contribution to PPARγ expression relatively small." (PMID 30674959, 2019). "Importantly, we showed that blocking lipid uptake/signaling by either inhibiting CD36 or PPARγ was highly effective in reducing TGF-β to these combined exposures, suggesting targeting these molecules might be effective in the treatment of silicosis." (PMID 30674959, 2019).
Sjögren's syndrome (4 papers, 2018 to 2024). "Reduced PPARγ expression and its transcriptional activity are observed in the labial salivary gland of primary Sjögren’s syndrome (pSS) patients, and promotes inflammation in the ductal epithelia via activated NF-kappa B pathways." (PMID 38714918, 2024). "PPARγ upgrades Sjögren’s syndrome, the over-expressive regulation of cytokines within the peripheral blood or salivary gland, in non-obese diabetic mice." (PMID 36902220, 2023). "The data presented here are related to the research article entitled “Impaired anti-inflammatory activity of PPARγ in the salivary epithelia of Sjögren's syndrome patients imposed by intrinsic NF-κB activation”." (PMID 29876386, 2018). "Moreover, in epithelial cells, including salivary duct cells, PPARg mediates anti-inflammatory effects and impaired functions contribute to Sjogren’s syndrome." (PMID 39203770, 2024).
skin infection (4 papers, 2019 to 2023). An inflammatory process affecting the skin, caused by bacteria, viruses, parasites, or fungi. "PPARγ is also critical for clearance of methicillin resistant Staphylococcus aureus (MRSA) in skin infections." (PMID 30897154, 2019). "Myeloid cell PPARγ signaling was essential for maintaining the resolution phase of MRSA skin infections in mice, and activation of PPARγ hastened the onset of wound resolution." (PMID 30897154, 2019). "Furthermore, PPARγ also enhanced the clearance of Pseudomonas aeruginosa (P. aeruginosa) and the resolution of S. aureus skin infections and S. aureus brain abscesses." (PMID 33927725, 2021). "Interestingly, a previous study has shown that PPARγ agonist treatment improves bacterial clearance in Staphylococcus aureus skin infection." (PMID 31159430, 2019).
thyroid (4 papers, 2004 to 2022). "Early in the histologic progression of thyroid disease in this TRβPV/PV mouse model expression of PPARγ mRNA, assessed byNorthern blot analysis, was diminished approximately 50% compared to wild-typesiblings." (PMID 18989374, 2008). "A number of studies, using RT-PCR, nested PCR, FISH, or Western analysis,have confirmed the relatively high prevalence of the PAX8/PPARγ rearrangement or expression of PPFP infollicular thyroid lesions, though the precise incidence varies by cell typeand method of detection." (PMID 18989374, 2008).
acute pancreatitis (3 papers, 2016 to 2017). An acute inflammatory process that leads to necrosis of the pancreatic parenchyma. "In addition, AA’s upregulation of TLR4 and downregulation of PPARγ may be associated with acute pancreatitis." (PMID 28424593, 2017).
alcoholic liver diseases (3 papers, 2019 to 2024). A disorder caused by damage to the liver parenchyma due to alcohol consumption. "Above results showed that magnolol could prevent alcoholic liver damage, and the underlying mechanism was through activating PI3K/Nrf2/PPARγ signaling pathways as well as inhibiting NLRP3 inflammasome, which also suggested magnolol might be used as a potential drug for ALD." (PMID 31920652, 2019).
ankylosis (3 papers, 2020 to 2024). Fixation and immobility of a joint. "In this study, we aimed to decipher whether lipocalin 2 and its association with PPARγ mediate the gut-joint axis, by using the ank/ank mutant mouse model with concurrent progressive ankylosis and subclinical gut inflammation." (PMID 32188494, 2020). "In summary, lipocalin 2 modulated by PPARγ could be a potential pathway involved in concurrent inflammation and ankylosis in AS and IBD." (PMID 32188494, 2020). "As elevated LCN2 levels implicate ongoing gut inflammation and progressive spinal ankylosis, our findings suggest that normalization of LCN2 through modulation of PPARγ could be viewed as a treatment target in AS and IBD." (PMID 32188494, 2020).
aortic aneurysm (3 papers, 2023 to 2025). A ruptured aneurysm located in the wall of the proximal portion of the descending aorta proceeding from the arch of the aorta. "Although currently there are no available agonists for PRDM16, it has been shown that PPARγ agonists could potently increase the half-life of the PRDM16 protein and PPARγ agonists attenuate inflammation in aortic aneurysm patients." (PMID 37079380, 2023).
atrial fibrillation (3 papers, 2016 to 2022). A disorder characterized by an electrocardiographic finding of a supraventricular arrhythmia characterized by the replacement of consistent P waves by rapid oscillations or fibrillatory waves that vary in size, shape and timing and are accompanied by an irregular ventricular response. "Thereby, TCONS_00016478 can affect the atrial energy metabolism remodeling and atrial fibrillation in experimental rabbits by regulating the PGC1-α/PPARγ signaling pathway." (PMID 34969364, 2022).
autoimmune thyroid disease (3 papers, 2014 to 2025). Inflammatory disease of the thyroid gland due to autoimmune responses leading to lymphocytic infiltration of the gland. "Future studies with PPARγ agonists in autoimmune thyroid diseases are necessary to determine any such effect." (PMID 27403442, 2016). "Besides controlling glucose metabolism and fatty acid storage, PPARγ is strongly expressed in the thyroid tissues of patients with autoimmune thyroid disease." (PMID 27403442, 2016).
B-cell lymphoma (3 papers, 2015 to 2023). "Our lab used the Ramos B cell lymphoma cell line transfected with a dominant negative (DN) PPARγ construct to block the activity of endogenous PPARγ." (PMID 26713087, 2015).
bacteremia (3 papers, 2021 to 2025). "Modulation of the macrophage response to an M2-like response was shown to facilitate resolution of S. aureus skin and soft tissue infections (SSTIs) and bacteremia via upregulation of peroxisome proliferator-activated receptor gamma (PPARγ)." (PMID 35575507, 2022).
benign breast disease (3 papers, 2009 to 2019). "PPARγ expression is reduced in human benign breast disease and cancers correlating with increased cyclin D1 abundance." (PMID 19356226, 2009).
brain cancer (3 papers, 2012 to 2023). A primary or metastatic malignant neoplasm affecting the brain. "Interestingly, a recent study in brain cancer reported the effect of the PPARγ inverse agonist T0070907, which is structurally very similar to GW9662." (PMID 34984327, 2022).
breast adenocarcinoma (3 papers, 2018 to 2022). "PPARγ has significant expression in human mammary adenocarcinomas and reduces the tumor growth of malignant breast epithelial cells." (PMID 35190574, 2022). "Among them, a sterol, 3β,11-dihydroxy-9,11-secogorgost-5-en-9-one (compound 1), showed the highest PPARγ activity with an IC50 value of 8.3 μM for inhibiting human breast adenocarcinoma cell (MCF-7) growth." (PMID 30018246, 2018).
breast ductal carcinoma (3 papers, 2019 to 2022). "PPARγ had a significantly favorable effect on recurrence-free survival in breast ductal carcinoma patients (p = 0.027) and was an independent prognostic factor in ductal carcinoma patients (p = 0.039)." (PMID 36611922, 2022).
cerebrovascular disease (3 papers, 2015 to 2024). "The combination of advanced glycation end products and corresponding receptors directly or indirectly leads to the occurrence and development of cerebrovascular disease, whereas reduced PPARγ expression can exacerbate this central nervous injury." (PMID 30100873, 2018). "And our research shows that 15d-PGJ2 can inhibit immune response and alleviate ischemic injury in the reperfused organs by activating PPARγ which could be a new target for cerebrovascular disease treatment." (PMID 26844229, 2015). "The TFs-gene regulatory networks identified the core TFs including PPARG, FOXC1 and GATA2, known for their roles in the inflammation regulation in the cerebrovascular diseases." (PMID 39469068, 2024).
Chagas disease (3 papers, 2012 to 2020). A parasitic infection caused by Trypanosoma cruzi. "Taking all this into account, our group has led research on the effect of different PPAR agonists in the context of Chagas disease, that bear in common anti-inflammatory properties besides their effect on carbohydrate (PPARγ) or lipid (PPARα) metabolism." (PMID 33072115, 2020). "We consider that PPARγ agonists might be useful as coadjuvants of the antiparasitic treatment of Chagas disease, to delay, reverse, or preclude the onset of heart damage." (PMID 29312293, 2017).
childhood asthma (3 papers, 2012 to 2022). "Nevertheless, the fact that a PPARγ agonist attenuates the effect of nicotine on sperm large and small RNA transcriptome further supports the notion that PPARγ agonists is a promising class of drugs for treating childhood asthma." (PMID 35600600, 2022).
co-infection (3 papers, 2015 to 2024). "This seems to be confirmed by the results of the present study, which indicate significantly less activation of PPARγ in the case of co-infection than in the case of TBEV infection alone." (PMID 38438941, 2024). "We also hypothesized that reduced PPARα and PPARγ expression would accelerate the process of liver fibrosis in patients with HIV/HCV co-infection." (PMID 26735218, 2015). "In multivariate linear regression analyses, only HIV-co-infection (p=0.001) and non-black race (p=0.04) were independently associated with lower PPARγ expression." (PMID 26735218, 2015). "PPARγ expression in HCV-infected livers was further reduced by HIV co-infection." (PMID 26735218, 2015). "Similarly, BMP9-induced expression of chondrogenic regulator Sox9 and adipogenic regulator Pparγ was also effectively diminished by AdR-simRmst co-infection, suggesting that Rmst may be an important mediator of BMP9-induced multiple-lineage differentiation of MSCs." (PMID 31825894, 2019). "However, in the case of bacterial co-infections, only increased expression of CB1, TRPV1 and PPARγ is observed." (PMID 38438941, 2024).
corneal diseases (3 papers, 2020 to 2024). "The combination ophthalmic solution of fenofibrate and pioglitazone suppressed inflammation, neovascularization, and fibrotic changes by a dual therapeutic effect of the PPARα and PPARγ agonists in the alkali-burned cornea, suggesting a new candidate therapeutic strategy for corneal disease." (PMID 32707656, 2020).
dengue (3 papers, 2010 to 2022). "We observed that dengue downregulated the expression of PPARγ and its coactivator PGC1α and also downregulated the expression of NRF2 and TFAM." (PMID 36197108, 2022). "PPARγ has been shown to play a critical role in the control of adipocyte differentiation and lipid metabolism, and also immunity and the barrier functions of epithelial and endothelial cells; in dengue disease this could be a response to epithelial stress." (PMID 21810247, 2011).
Ductal carcinoma in situ (3 papers, 2008 to 2019). "Treatment of ductal carcinoma in situ relied on efatutazone (a PPARγ agonist), leading cells to be less invasive and show elevated differentiation." (PMID 31661894, 2019). "We thus concluded that Five genes: CDK1, CCNB2, MAD2L1, PPARG, ACACB were finally identified to participate in the regulation and serve as potential diagnosis signatures in in Ductal carcinoma in situ." (PMID 28977921, 2017).
Dyskinesia (3 papers, 2018 to 2022). A movement disorder which consists of effects including diminished voluntary movements and the presence of involuntary movements. "In addition, the antidyskinetic effects of URB597 in combination with capsazepine were reversed by a non-selective PPAR antagonist, and in the same model a PPARγ selective agonist showed a significant reduction of dyskinesia." (PMID 29910713, 2018).
E. coli infection (3 papers, 2016 to 2022). "The expression of genes and proteins related to fatty acid anabolism was downregulated by E. coli infection, including SREBP1, SCD, FAS, and PPARγ." (PMID 36341408, 2022).
endometritis (3 papers, 2021 to 2026). An acute or chronic, usually bacterial infectious process affecting the endometrium. "Similarly, expressions of IFNT, ISG15, CXCL10, PPARG, RXRG, SLC2A1, and SLC27A6 proteins were greater and MUC1 was lower in the endometrium of cows without endometritis compared with cows with endometritis (p < 0.05)." (PMID 33920430, 2021).
female infertility (3 papers, 2012 to 2024). Diminished or absent ability of a female to achieve conception. "This double-edged nature of PPARγ makes it an interesting target for future therapeutic interventions targeting reproductive disorders related to female infertility." (PMID 38994935, 2024). "In the context of female infertility, PPARγ may potentially disrupt the regeneration of endometrium after menstruation through the inhibition of endometrial angiogenesis resulting in the abnormal endometrial functions." (PMID 38994935, 2024).
Graves ophthalmopathy (3 papers, 2021 to 2022). An autoimmune disorder of the EYE, occurring in patients with Graves disease. "Also, evidence indicates CCL2 and CXCL10 chemokine modulations by cytokines and PPARγ agonist in Graves’ ophthalmopathy." (PMID 34054797, 2021). "Also, evidence indicated that CCL2 and CXCL10 chemokines, modulated by cytokines and PPARγ agonist, play an important role in Graves’ ophthalmopathy." (PMID 35242125, 2021).
hyperplasia (3 papers, 2020 to 2023). An abnormal increase in the number of cells in an organ or a tissue with consequent enlargement. "The mRNA and protein levels of PPARγ were more than four times and three times higher in the normal prostate than in the hyperplastic prostate, respectively." (PMID 36902342, 2023).
leishmaniasis (3 papers, 2012 to 2015). Infectious disease that is transmitted through the bite of hematophagous female phlebotomine sand flies. "PPARG was previously associated with susceptibility to leishmaniasis." (PMID 23029578, 2012). "In experimental models of leishmaniasis, upregulation of PPARγ by IL-4 was demonstrated to instill monocytes/macrophages with potent anti-inflammatory and Th2 functionalities, essential for disease progression." (PMID 26496711, 2015).
Listeria monocytogenes infection (3 papers, 2012 to 2023). "Loss of PPARγ in myeloid cells results in enhanced innate immune defense against Listeria monocytogenes infection both, in vitro and in vivo." (PMID 22629382, 2012). "Here we address this question and provide clear evidence that PPARγ restricts innate immunity in myeloid cells against Listeria infection." (PMID 22629382, 2012). "Taken together, these results strongly suggested that Listeria infection not only led to increased expression of PPARγ but also increased activity as transcriptional regulator." (PMID 22629382, 2012). "We found that Listeria monocytogenes infection of macrophages rapidly led to increased expression of PPARγ." (PMID 22629382, 2012). "Conditional deletion of PPARγ in myeloid cells in mice showed a hyperinflammatory response to infections to promote pathogen clearance in response to Mycobacterium tuberculosis, Salmonella typhimurium, Brucella abortus, and Listeria monocytogenes infection." (PMID 36928191, 2023). "Our results elucidate a yet unknown regulatory network in myeloid cells that is governed by PPARγ and restrains both listeriocidal activity and recruitment of inflammatory monocytes during Listeria infection, which may contribute to bacterial immune escape." (PMID 22629382, 2012). "This prompted us to investigate whether PPARγ in myeloid cells influences innate immunity against Listeria monocytogenes infection by using transgenic mice with myeloid-cell specific ablation of PPARγ (LysMCre×PPARγflox/flox)." (PMID 22629382, 2012). "LysM- PPARγKO mice showed an improved survival compared to wildtype littermates, indicating that absence of PPARγ in myeloid cells enhances innate immune defense against Listeria infection." (PMID 22629382, 2012). "Importantly, increased resistance against Listeria infection in the absence of PPARγ was not accompanied by enhanced immunopathology." (PMID 22629382, 2012). "To address the question whether the gain of function upon PPARγ ablation in macrophages is already sufficient to improve control of Listeria infection in the absence of inflammatory monocytes, we adoptively transferred PPARγ-deficient macrophages into CCR2−/− mice." (PMID 22629382, 2012).
mental disorder (3 papers, 2020 to 2022). A disease that has its basis in the disruption of mental process. "Similarly, PPARγ and PPARδ have well-described roles in the regulation of mitochondrial function and PPAR-γ has even been investigated as a therapeutic target for mental disorders in this regard." (PMID 35941107, 2022).
metastatic melanoma (3 papers, 2012 to 2018). A melanoma that has spread from its primary site to another anatomic site. "PPARγ is a late stage predictive marker in metastatic melanoma, and PFS is significantly improved by adding pioglitazone to a pro-anakoinotic schedule, including metronomic low-dose chemotherapy and COX-2 inhibitor." (PMID 30424016, 2018). "Using Oncomine database, we found that the mRNA levels of FAK, Src, ERK1/2 and Stat3 increased, while the mRNA levels of PPARγ, C21orf34 (miR-125b host gene) and E-cadherin decreased in human metastatic melanoma." (PMID 28108732, 2017). "PPARγ expression in metastatic melanoma was shown to be a possible predictive marker for response to biomodulatory stroma-targeted therapy, since patients with PPARγ-positive metastases showed a significantly prolonged progression-free survival treated with biomodulatory treatment." (PMID 23049949, 2012). "In metastatic melanoma, the addition of pioglitazone to metronomic low-dose chemotherapy and COX-2 inhibitor has important therapeutic impact on outcome, as indicated in the paragraph ‘PPARγ agonist plus COX-2 inhibitor’." (PMID 30424016, 2018).